ENSG00000252945
Synonyms: LOC124903423
Gene: Small nucleolar RNA gene on chromosome 14 (50,844,625 to 50,844,712, forward strand). Ensembl gene ENSG00000252945.
Gene Ontology:
Biological process: RNA processing
Cellular component: nucleolus
Homologues: Paralogues in human: SNORD83B (64% identical), SNORD83A (61% identical).